IL13 (interleukin 13)
Diseases named in the same sentence as IL13 in open-access papers (continued):
Sharing a sentence is not in itself a finding about the gene and the disease.
eosinophilic esophagitis (40 papers, 2012 to 2026). Eosinophilic esophagitis (EoE) is a chronic, allergic disease of the esophagus characterized clinically by symptoms of esophageal dysfunction (including vomiting, dysphagia, feeding disorders, food impaction and abdominal pain) which persist after treatment with proton pump inhibitors (PPIs). "Abnormalities in estrogen genes, including ESR1, have been observed in conditions like eosinophilic esophagitis, influencing esophageal barrier function, caused by increased IL-13." (PMID 38414734, 2024). "IL-13 has been closely linked to the pathogenesis of a food allergic disorder, eosinophilic esophagitis both in animal studies and in clinical samples obtained from individuals with allergic disorder." (PMID 21961022, 2012). "Eosinophilic esophagitis (EoE), an allergic inflammation of the esophagus, provides a striking example: IL‐13–driven inflammation in EoE causes esophageal epithelial cells to downregulate E‐cadherin and acquire mesenchymal markers, contributing to tissue stiffening and dysmotility." (PMID 40679787, 2025). "Eosinophilic esophagitis (EoE) is a chronic, Th2-associated inflammatory disorder characterized by pronounced inflammation of the esophagus with cytokines such as Il-5, Il-13, Il-4, and IgE that contribute significantly to the EoE pathogenesis, similarly to AD." (PMID 38256267, 2024). "Dupilumab is a monoclonal antibody targeting interleukin-4 and interleukin-13, approved for the treatment of multiple T2 diseases and more recently for Eosinophilic Esophagitis (EoE)." (PMID 39906352, 2024). "LRRC31, characterized by its nine leucine‐rich repeats, is induced by interleukin 13 to regulate esophageal epithelial barrier function in eosinophilic esophagitis." (PMID 38098610, 2023). "In murine models, the intratracheal administration of IL-13 induced eosinophilic esophagitis with a dose-dependent trend." (PMID 36140492, 2022). "The authors detected a hypomethylation and increased expression of NTRK1 in atopy; this gene is induced by interleukin 13 (IL-13) and is increased in eosinophilic esophagitis." (PMID 32500051, 2020). "Opposite to what happens in the intestine, miR-375-3p is down-regulated in the lung of an IL-13 lung-transgenic mouse model, and is down-regulated in patients with eosinophilic esophagitis (EE), compared to healthy volunteers." (PMID 32155783, 2020). "miR-375 has also been reported to be downregulated in epithelial cells derived from patients with eosinophilic esophagitis, as well as in IL-13 stimulated epithelial cells indicating the role of miR-375 as a regulator of IL-13-mediated responses." (PMID 29467760, 2018). "The lncRNA BANCR was upregulated in eosinophilic esophagitis, which is another allergic inflammatory disorder, and was induced in IL-13 that treated primary esophageal epithelial cells." (PMID 28057064, 2017). "This disease, termed eosinophilic esophagitis (EOE), is associated with a Th2 immune profile and synthesis of the cytokine IL-13, which has direct cytotoxic effects on epithelial cells." (PMID 24678255, 2013). "Dupilumab has demonstrated significant efficacy in eosinophilic esophagitis by reducing eosinophilic inflammation through inhibition of IL-4 and IL-13 signaling pathways, and thus could theoretically exert similar beneficial effects in EoEM." (PMID 40884722, 2025). "Some research pointed out that IL-13 could influence the epithelial cells' proliferation in eosinophilic esophagitis, tumor cells, but in CRSwNP, the function of IL-13 in proliferation activity is not explored enough." (PMID 40438321, 2025). "Additionally, IL-13 receptor alpha 2 has been found to inhibit the detrimental tissue remodeling induced by IL-13 in murine models of both lung inflammation and eosinophilic esophagitis, a chronic inflammation of the esophagus." (PMID 33526116, 2020).
eosinophilic esophagitis (continued). "Eosinophilic esophagitis (EoE) is a chronic, allergic inflammatory disorder of the esophagus that is characterized by interleukin 13 (IL-13)–mediated esophageal epithelial cell differentiation and barrier defects." (PMID 26039063, 2015). "In eosinophilic esophagitis (EoE), food allergens trigger a T-helper 2 (Th2) immune response with production of Th2 cytokines such as interleukin (IL)-13 and IL-4." (PMID 24988451, 2014). "In the HOME0-grown organoids, IL-13 and UAB30 induced epithelial changes reminiscent of basal cell hyperplasia, a common histopathologic feature in broad esophageal disease conditions including eosinophilic esophagitis." (PMID 39334892, 2024). "Besides, IL-13 has been implicated in inflammation and remodeling by inducing chemokines (CCL-3, CCL-4, CCL-5 and CXCL-1), and IL-13 is a direct inducer of both CCL11 and CCL24 in eosinophilic esophagitis." (PMID 27533463, 2016).
influenza (40 papers, 2009 to 2025). An acute viral infection of the respiratory tract, occurring in isolated cases, in epidemics, or in pandemics; it is caused by serologically different strains of viruses (influenzaviruses) designated A, B, and C, has a 3-day incubation period, and usually lasts for 3 to 10 days. "AAM and the secretion of IL‐4 and IL‐13 have also been implicated in the increased susceptibility of mice to a secondary pneumococcal infection during recovery of influenza infection." (PMID 29119707, 2018). "Some of the cytokines were very low in the PBS group, especially the signatures for T-cell responses such as IL-4, IL-5, and IL-13, which is in line with the typical type 1 skewed host immune response to influenza infection." (PMID 38711520, 2024). "Similar findings were made in another study in allogeneic HSCT patients, in which the number of IL-13 producing T-cells, stimulated by influenza peptides, increased significantly after seasonal influenza vaccination in all HSCT patients." (PMID 34452033, 2021). "For example, it reported that IL-28B is an important regulator of the Th1/Th2 balance by increasing Th1-type cytokines (IFN-γ) and decreasing Th2-type cytokines (IL-4, IL-5 and IL-13) during influenza vaccination." (PMID 34818327, 2021). "In a subset of individuals, the bacterially produced recombinant VLP-based influenza vaccine shifted pre-vaccination-induced type-2 cytokines such as IL-5 and IL-13 to a post-vaccination type-1 cytokine signature characterized by IFN-γ." (PMID 33800349, 2021). "For example, IL-33 receptor ST2 signaling drives type 2 immune pathology during respiratory viral infection; IL-33 mediates influenza airway pathology by eliciting IL-13 production by innate lymphoid cells." (PMID 33857419, 2021). "In mouse studies, IL-4 and IL-13 production was also observed following vaccination with an inactivated influenza/AS03 formuation." (PMID 33688652, 2021). "In mouse studies, IL-4 and IL-13 production was also observed after vaccination with an inactivated influenza/AS03 formulation." (PMID 34315825, 2021). "Overall, when we compared the relative contribution of CD4+ T cells and ILC2s to the population of type 2 cytokine expressing cells, it was apparent that CD4+ T cells were the major source of IL‐5 or IL‐13 in the early phase of influenza‐induced exacerbation." (PMID 29762870, 2019). "This capacity of the gH1-Qbeta vaccine to preferentially elicit IFN-γ is seen in a subset of individuals whose pre-existing influenza-specific cytokine responses were characterized by the T helper type 2 (Th2) cytokines IL-5 and IL-13." (PMID 30573748, 2018). "SOCS1−/−IFN-γ−/− mice exhibited significantly decreased production of IL-6 and IL-10 at 7 dpi but increased IL-4, IL-5 and IL-13 levels in airways during influenza infection." (PMID 25500584, 2014). "We also found that pulmonary iNKT cells from PD-L2−/− mice produce more IL-4 and IL-13 after influenza infection." (PMID 23555047, 2013). "Here, pulmonary VV inoculation mirrored influenza infection as pulmonary transcripts for IL-5, IL-13, and IL-17 were significantly decreased in VV-infected mice with AAD." (PMID 23620814, 2013). "In mice, genetic deletion of Cnr2 exacerbated contact allergic inflammation and influenza-induced excessive airway injury possibly via induction of pro-inflammatory and pro-remodeling mediators (IL-17, IL-13, TNF-α, GM-CSF)." (PMID 23844029, 2013). "The ability of the gH1-Qbeta VLP vaccine to influence the quality of the cytokine response was further emphasized in specific individuals whose pre-existing influenza responses were characterized by a higher level of the Th2 cytokines IL-5 and IL-13 over the Th1 cytokine IFN-γ." (PMID 30573748, 2018). "Interestingly, while infants are capable of mounting robust type-1 responses to other respiratory viruses such as influenza, they uniquely favor type-2 responses and the development of Th2 adaptive immunity (i.e. elevated IL-13 compared to IFN-γ) to RSV." (PMID 26473724, 2015).
influenza (continued). "Using influenza as a model, live attenuated and killed inactivated influenza vaccines stimulate many shared pathways such as signaling of many interleukins (including IL-1, IL-4, IL-6, IL-13, IL-20, and IL-27), interferon signaling, MARK1 activation, and neutrophil degranulation." (PMID 33777032, 2021). "After 14 days of LS intervention, the levels of IL-1ra, Eotaxin, IFN-γ, IL-6, IL-10, IL-13, SCF and TRAIL in serum of participants with influenza infection were significantly decreased compared with Placebo group." (PMID 36034844, 2022). "After 14 days of LS intervention, the levels of IL-1ra, IL-6, IL-10, IL-13, Eotaxin, IFN-γ, SCF and TRAIL in serum of participants with influenza infection were significantly decreased compared with Placebo group (p < 0.05 or p < 0.01)." (PMID 36034844, 2022). "A larger drop in IL-13 response was noted in MUOO adolescents between baseline and one-month post-influenza vaccine compared to MHOO and NWC, suggesting that there is a yet-unidentified diminished immunologic response in this population." (PMID 35062328, 2022). "MC-derived cytokines of potential interest in suppressing influenza immunopathology include: TNFα, TGF-β1, GM-CSF, IL-2, IL-9, IL-13, and IL-33." (PMID 33680987, 2021). "Administration of the novel virus-like particle based vaccine elicited influenza-specific CD4+ and CD8+ T-cell responses and the induction of the cytokines IFN-γ, IL-17A, IL17F, IL-5, IL-13, IL-9, IL-10 and IL-21." (PMID 30573748, 2018). "While an RSV infection of allergic animals results in enhanced Th2 cytokine production in the lungs, influenza respiratory challenge of AAD mice reduced lung IL-4, IL-5, and IL-13 expression." (PMID 23620814, 2013). "Next the effects of DEP prior to infection with influenza in OVA-sensitized mice on the expression of inflammatory cytokines were examined, with a specific focus on TH2 cytokines, including IL-13 and IL-4." (PMID 19682371, 2009). "Taken together, these data show that in OVA-sensitized mice, exposure to DEP prior to infection with influenza enhanced the expression of the TH2 cytokines IL-4 and IL-13 and their common receptor IL-4Rα." (PMID 19682371, 2009). "In the pathway analysis, inflammatory-immune disease (e.g., IBD, influenza, and RA) and the related pathways (e.g., the IL-17 signaling pathway, the NOD-like receptor signaling pathway, interleukin-4 and interleukin-13 signaling, and signaling by interleukins) were enriched among the AFgenes." (PMID 39742001, 2024). "In each of the models, CD4+ T cells are recruited to the site of inflammation, and each type of infection is dominated by the corresponding TH cell subset, in numbers and proportions; Influenza by TH1 cells (IFNγ), N. brasiliensis by TH2 cells (IL-4, IL-13), and A. fumigatus by TH17 cells (IL-17)." (PMID 37696824, 2023). "Cytokines such as IL-4, IL-5, IL-6, IL-8, IL-13, and TNF-α, chemokines such as CCL2 and CCL3, and the MC proteases tryptase and chymase can be detected in the supernatants of influenza infected MC cultures and in the bronchioalveolar lavage fluid (BALF) of both influenza patients and infected mice." (PMID 33680987, 2021). "In addition, IFN-λ increases influenza-induced Th1 cytokines (IFN-γ, IL6), whereas influenza-induced Th2 cytokines decrease (IL4, IL5, IL9, IL13)." (PMID 28293236, 2017). "To determine the possible impact of ST2 on pulmonary inflammation during influenza infection, we measured lung levels of cytokines (IFN-γ, TNF-α, IL-1β, IL-6, IL-10, IL-33, IL-13, IL-5) and chemokines (KC, MIP-2) at 3, 8 and 14 days following influenza inoculation." (PMID 23483993, 2013). "TNFα remained below the limit of detection during influenza infection, whereas IL-5 and IL-13 were not induced by influenza infection (data not shown)." (PMID 23483993, 2013). "Exposure to DEP or infection with influenza alone resulted in a small, but not statistically significant enhancement of IL-13." (PMID 19682371, 2009).
influenza (continued). "In addition Th2-type cytokines, such as IL-4 and IL-13, and markers of eosinophil chemotaxis, such as CCL11 and CCR3, were increased in OVA-sensitized mice exposed to DEP prior to infection with influenza." (PMID 19682371, 2009). "Indeed, it was clearly shown that the mere transgenic expression of Muc5ac, without the involvement of (IL-13-driven) inflammatory responses, is protective in influenza infections." (PMID 25398130, 2014). "However, despite the polarization towards a Th2 phenotype, IL-13 levels were not different in this model (data not shown) suggesting that DE enhanced influenza infection may specifically increase Th2 cytokines induced in influenza such as IL-4." (PMID 21092162, 2010). "In striking contrast, NKT cells represent up to 50%–70% of the total IL-4+ cells after influenza infection; however, we did not detect NKT cell production of other type 2 cytokines, such as IL-5 and IL-13." (PMID 29249358, 2018). "In addition, these children received an influenza vaccine and similarly it was found that the IFN-γ response to influenza was higher in non-infected children, whereas IL-5 and IL-13 production was increased in infected children." (PMID 23272112, 2012). "CK5 also shared similar correlations with CK14 for IL-1a and IL-13 in FLU− populations; however, beyond these highlights, the expression of CK5 did not correlate with many of the cytokine expressions exhibited with other cytokeratins, regardless of influenza positivity of the cells." (PMID 39791909, 2025).
malaria (40 papers, 2009 to 2025). Malaria is a serious and sometimes fatal disease caused by a parasite that commonly infects a certain type of mosquito which feeds on humans. "It has been observed that clinical or severe malaria is associated with increased levels of pro-inflammatory cytokines, including IL-1β, IL-6, IL-8, IL-10, IL-12, IL-13, IL-31, IL-33, and TNF-α." (PMID 39204168, 2024). "(2009) studied 82 SNVs within a 522-kb region on chromosome 5q31-33 and observed two haplotypes encompassing the entire RAD gene and the promoter of IL13 bearing the C allele of rs188147 conferring protection to severe malaria." (PMID 37908348, 2023). "Multinominal regression analyses adjusted for age and gender revealed that severe malaria was associated with higher levels of IL-2 (p = 0.025) and IL-13 (p = 0.018) than malaria with hyperbilirubinaemia." (PMID 26466783, 2015). "In Thailand, the functional IL-13−1055*T allele has been shown to enhance resistance to severe malaria through the alteration of IL-13 production." (PMID 23668806, 2013). "Among the inflammatory mediators implicated in malaria pathogenesis is interleukin (IL)-13, a type 2 cytokine that shares structural and functional characteristics with IL-4." (PMID 23521898, 2013). "IL-12 and IL-13 were also associated with having had previous malaria episodes (proportional difference = 1.35 [1.02-1.77], P = 0.0340; proportional difference = 1.32 [1.04-1.67], P = 0.0234)." (PMID 22280502, 2012). "Concerning IL-13, an SNP −1055T>C (rs1800925) has showed a significant association with protection from severe malaria in Thailand." (PMID 23316245, 2012). "High IL-13 was also positively associated with incidence of malaria as analysed by all methods but only during the second year." (PMID 22280502, 2012). "Higher frequencies of IFN-γ and IL-10 producing CD3+ cells and elevated IL-10, IFN-γ, MCP-1 and IL-13 in plasma were individually associated with increased malaria incidence, at different time points." (PMID 22280502, 2012). "Plasma concentrations of IL-10, IL-12 and IL-13 were associated with current infection or prior malaria episodes." (PMID 22280502, 2012). "A fine association mapping in the IL-13 gene using the same malaria subjects revealed that only rs1881457 located in the promoter region, which is in linkage disequilibrium with rs1800925, showed a significant association with severe malaria." (PMID 23316245, 2012). "Only rs1881457 located in the promoter region of IL13, which is in linkage disequilibrium with rs1800925 (r2 = 0.73), showed a significant association with severe malaria after adjusting for multiple testing (P = 0.046 by permutation test)." (PMID 19840389, 2009). "It has been previously demonstrated that a single nucleotide polymorphism (SNP) in the IL13 promoter region, IL13 -1055T>C (rs1800925), was associated with susceptibility to severe malaria in Thais." (PMID 19840389, 2009). "Of which, a SNP in the IL13 promoter region, IL13 -1055T>C (rs1800925), was found to be associated with susceptibility to severe malaria in Thais." (PMID 19840389, 2009). "A haplotype block spanning 97 kb encompassing RAD50 gene and IL13 promoter region that was associated with severity of malaria was identified in a Thai population." (PMID 19840389, 2009). "In addition, studies in Thai adults demonstrated that a single nucleotide polymorphism (SNP) in the IL-13 promoter (IL-13 -1055C > T) is associated with severe malaria." (PMID 23521898, 2013). "Finally, the IL-13−1055*T allele is found in individuals who present enhanced IL-13 production and seem protected against severe malaria." (PMID 23668806, 2013). "The fact that IL13 resides in the human chromosome 5q31–33 region and has been shown to influence the clinical outcome of malaria as well as immunoglobulin E (IgE) levels raises the possibility of association of its variants with malaria severity." (PMID 24312262, 2013).